STAC (SH3 and cysteine rich domain)
Description:
Promotes expression of the ion channel CACNA1H at the cell membrane, and thereby contributes to the regulation of channel activity. Plays a minor and redundant role in promoting the expression of calcium channel CACNA1S at the cell membrane, and thereby contributes to increased channel activity. Slows down the inactivation rate of the calcium channel CACNA1C.
Synonyms: STAC1
Tractability: Antibody: UniProt places it where antibodies can reach, with medium confidence; its Gene Ontology location is reachable by antibodies, with medium confidence.
Gene: Protein-coding gene on chromosome 3 (36,380,321 to 36,548,045, forward strand). Ensembl gene ENSG00000144681.
Subcellular location: Cytoplasm, cytosol; Cell membrane; Cell membrane, sarcolemma
Subcellular location (Human Protein Atlas): Nucleoplasm; Plasma membrane
Gene Ontology:
Molecular function: protein binding; calcium channel regulator activity; transmembrane transporter binding
Biological process: positive regulation of cation channel activity; positive regulation of protein localization to plasma membrane; positive regulation of voltage-gated calcium channel activity; signal transduction; skeletal muscle contraction
Cellular component: cytoplasmic side of plasma membrane; cytosol; plasma membrane; sarcolemma; T-tubule
Genetic constraint (gnomAD): Loss-of-function variants: 38 observed, 42.19 expected, observed/expected ratio (o/e) 0.9, 90% interval 0.69 to 1.18. The upper end of that interval is the gene's LOEUF score, 1.18, which puts it in group 5 of 6, group 1 being the genes least tolerant of losing a copy. Missense variants: 461 observed, 477.49 expected, observed/expected ratio (o/e) 0.97, 90% interval 0.89 to 1.04. Synonymous variants: 177 observed, 170.55 expected, observed/expected ratio (o/e) 1.04, 90% interval 0.92 to 1.18.
Homologues: Orthologues: chimpanzee STAC (99% identical), macaque STAC (98% identical), pig STAC (90% identical), rabbit STAC (90% identical), guinea pig STAC (89% identical), dog STAC (86% identical), rat Stac (84% identical), mouse Stac (83% identical), tropical clawed frog stac (70% identical), zebrafish stac (57% identical). Paralogues in human: STAC2 (46% identical), STAC3 (33% identical).
Diseases named in the same sentence as STAC in open-access papers:
STAC is named in the same sentence as 1 disease in open-access papers, as found by Europe PMC text mining. Sharing a sentence is not in itself a finding about the gene and the disease.
STAC shares sentences with these, for which no sentence is quoted: cancer (1 paper).